PUF60 (poly(U) binding splicing factor 60)
Diseases named in the same sentence as PUF60 in open-access papers (continued):
Sharing a sentence is not in itself a finding about the gene and the disease.
cancer (23 papers, 2010 to 2026). A tumor composed of atypical neoplastic, often pleomorphic cells that invade other tissues. "Both gain-of-function/dominant negative of FIR (overexpression of FIRΔexon2 in cancer) and loss-of-function of PUF60 (haploinsufficiency in VRJS) contribute to the pathology." (PMID 41596295, 2026). "Together, these results show that sensitive 3′ss previously identified by RNA-Seq in cells lacking PUF60 can provide useful substrates for rapid identification of functional cancer-associated RRM mutations not only in PUF60, but also in a cooperating protein." (PMID 32664474, 2020). "EMSA with WT PUF60 confirmed strong binding to a positive control derived from AdML and showed reduced binding of each cancer-associated RRM mutation that produced trans-acting defects." (PMID 32664474, 2020). "Together, these results indicated that the UBE2F reporter should be informative for testing splicing outcomes of cancer-associated RRM mutations in both proteins while OGDH is suitable for examining PUF60 variants." (PMID 32664474, 2020). "U2AF2 and PUF60 mutations in cancer cells are less restricted than those in SF3B1 or U2AF1; nevertheless, a previous study mapped recurrent mutations to U2AF65-RNA interfaces." (PMID 32664474, 2020). "It is also worth mentioning that some cancer-associated PUF60 substitutions, such as V230M or A231P, are at the same alignment positions that were previously implicated in side chain contacts between U2AF65 and U7 RNA." (PMID 32664474, 2020). "Here we have exploited publicly available RNA-seq data to develop screening assays of cancer-associated PUF60/U2AF65 RRM substitutions to identify functional mutations." (PMID 32664474, 2020). "COSMIC data showed that missense mutations in cancer patients were reported at relatively high frequencies, both in PUF60 (63%) and in U2AF65 (71%)." (PMID 32664474, 2020). "At least three RRM mutations increased skipping of internal U2AF2 (~9%, 2/23) or PUF60 (~8%, 1/13) exons, indicating that cancer-associated RRM mutations can have both cis- and trans-acting effects on splicing." (PMID 32664474, 2020). "Targeting PUF60 may complement therapies for cancers harboring splicing factor mutations (e.g., SF3B1, U2AF1)." (PMID 41596295, 2026). "Because UHM domain substitutions found in PD diminished PUF60 expression, cancer mutations in this domain could affect selection of PUF60-dependent 3′ss globally, potentially mimicking splicing abnormalities previously observed for the PUF60 knockdown." (PMID 32664474, 2020). "PUF60 overexpression is observed in many cancer types (e.g., breast, bladder, leukemia) and correlates with a poor prognosis." (PMID 41596295, 2026). "The results showed that the expression of DCP1A and PUF60 were both higher in cancer tissue than that in adjacent tissue." (PMID 37632669, 2024). "PUF60 was screened from the most amplification region in OC, so we first analyzed the copy number alteration in the cBioPortal for Cancer Genomics." (PMID 37632669, 2024). "The other functional molecule of interest in cancer progression is PUF60 (poly(U) binding splicing factor 60), a component of the spliceosome." (PMID 36497066, 2022). "In summary, PUF60 plays an important role in human diseases, including cancer and congenital diseases." (PMID 33117697, 2020). "In the present study, we employed PUF60- and/or U2AF65-dependent splicing reporters and biochemical assays to discover cancer-associated missense mutations in PUF60 and U2AF65 RRMs that impair protein function." (PMID 32664474, 2020). "Next, we confirmed the expression of PUF60 in TCGA datasets, and found significantly higher expression of PUF60 mRNA in carcinoma tissues compared to normal bladder tissues." (PMID 33117697, 2020). "These natural PUF60 isoforms were previously identified by RT-PCR and immunoblotting in cell lines and exhibited comparable cancer-promoting properties." (PMID 29788428, 2018).
cancer (continued). "PUF60, which ranked among the top ten oncogene candidates across all cancer types (sum of TS scores = 7, sum of OG scores = 19), but in BRCA, its TS score is as high as its OG score." (PMID 27321817, 2016). "RBM39 is involved in RNA splicing activation and transcription in cancer alongside FIR/PUF60." (PMID 41596295, 2026). "PUF60 (Poly (U)-binding splicing factor 60) is a nucleic acid-binding protein that has been shown to regulate transcription and link to tumorigenesis in various cancers." (PMID 39781520, 2025). "Recent studies have found that PUF60 overexpressed in various cancers." (PMID 37632669, 2024). "Interestingly, CNV and/or elevated expressions of PUF60 have been reported in multiple cancers, and thus cancer-promoting functions have been proposed for PUF60." (PMID 39408764, 2024). "All these evidences indicated that PUF60 might be one of the dominant factors that mediate the initiation and progression of various cancers by influencing some key biological processes or pathways." (PMID 33117697, 2020). "Further verification about the roles of PUF60 in different cancers is awaited." (PMID 33194730, 2020). "This suggests that U2AF65 and PUF60 RRM substitutions may turn out to be important contributors to the mRNA isoform diversity of cancer cells, acting both in cis and trans." (PMID 32664474, 2020). "However, the functional fraction of PUF60/U2AF65 mutations in their RNA recognition motifs (RRMs) is unknown and their impact on protein properties and cancer initiation is not fully understood." (PMID 32664474, 2020). "ATAD2, BRMS1L, PUF60, SHQ1, and USP4 were found to influence overall survival in 15, 9, 13, 13, and 12 of the 21 cancer types, respectively." (PMID 39127727, 2024). "For example, the present study provided new insights into the involvement of several members of the CanCord34 genes (i.e., EXOSC4, PUF60, and BOP1) in cell viability, cancer stem cell biology, and extracellular communications via secreted plasma vesicles." (PMID 36497066, 2022). "These putative BC progressor RBPs (PUF60, TFRC, KPNB1, NSF, and SF3A3) were integrated into a disease gene network to shed light on their molecular and cellular functions in cancer." (PMID 35453681, 2022). "To better understand the cellular functions of these prioritized RBPs (TFRC, KPNB1, PUF60, NSF, and SF3A3) in cancer, we next interrogated the HumanNet v2." (PMID 35453681, 2022). "PUF60 is required for cell viability, proliferation and migration in vitro and is often overexpressed in (pre-)malignant tissues, suggesting that the heterogeneity of missense RRM mutations in cancer cells might influence 3′ss/branch site recognition and expand mRNA isoform diversity." (PMID 32664474, 2020). "Other important candidates such as splicing factors PUF60 and XAB2 and TRAP1, a chaperone upregulated in various cancers and essential for maintaining mitochondrial homeostasis were downregulated in LSCs." (PMID 31448224, 2019). "Survival analysis showed that several of the dysregulated genes (e.g. ATAD2, BRMS1L, PUF60, SHQ1, and USP4) have an impact on prognosis in multiple cancer types, thereby further highlighting the clinical significance of aberrant gene expression patterns on patient survival." (PMID 39127727, 2024). "Neither PUF60 nor U2AF65 were identified among most dysregulated RBPs in a systematic expression screen across 15 cancer types." (PMID 32664474, 2020). "PUF60 was over-expressed in cancers with CNAs (P = 0.038), but its expression was not significantly different between tumor tissues and matched normal tissues in samples without CNAs (P = 0.111)." (PMID 26360582, 2015). "The PUF60 overexpression may facilitate detachment of cancer cells on a 3D matrix and their migration was promoted by PUF60 isoforms lacking exon 2/5." (PMID 32664474, 2020).
cancer (continued). "Under this hypothesis, we prepared FIR–FLAG, FIRΔexon2–FLAG or PUF60–FLAG stably expressing HeLa cells (cancer cells) or 293T cells (non-cancer cells), and pull-down assays were performed to examine whether FIR, DNA-PKcs and Ku86 interacted." (PMID 24811221, 2014). "The clustering of mutations within conserved domains would support their importance in cancer initiation or progression and the role of U2AF2 or PUF60 as oncogenes as opposed to tumor suppressors." (PMID 32664474, 2020).
tumor (16 papers, 2011 to 2026). "Based on the association of high PUF60 high expression with aggressive tumor behaviors, PUF60 may serve as a novel potential prognostic marker." (PMID 37632669, 2024). "For instance, PUF60 deletion alters CDC25 isoforms, causing cell cycle arrest at the G2/M phase in tumor cells." (PMID 41596295, 2026). "The stable PUF60-knockdown group showed a delay in the growth speed of tumors, as well as reduced tumor weight and volume." (PMID 37632669, 2024). "An obvious stimulation in the growth speed of tumors as well as increased tumor weight and volume were observed in the group stably overexpressing PUF60." (PMID 37632669, 2024). "As expected, PUF60 expression was closely correlated with tumor stage and subtype in OC, and highly aggressive subtypes such as clear-cell OC and high-grade serous OC often exhibit higher PUF60 expression levels." (PMID 37632669, 2024). "Similar experiments were performed to explore the effects of PUF60 overexpression on tumor growth in subcutaneous xenografts." (PMID 37632669, 2024). "In the present study, we identified PUF60 as one of the most differentially expressed genes between normal and tumor bladder tissues among the 97 RNA splicing proteins." (PMID 33117697, 2020). "Poly-U binding splicing factor 60 kDa (PUF60), a factor regulating RNA splicing, is closely involved in tumor progression." (PMID 32219041, 2020). "We found that PUF60 mRNA was significantly highly expressed in tumor tissues compared to normal bladder tissues in all four datasets." (PMID 33117697, 2020). "Additionally, Qihong Huang identified a novel ribonucleprotein (RNP) complex (hnRNPK, FXR1, FXR2, PUF60, SF3B3), which is required for translational regulation of lncRNA to cause tumor invasion and metastasis." (PMID 34057025, 2021). "In addition, PUF60 is closely related to c‐myc transcription and tumor processing." (PMID 40411278, 2025). "However, despite numerous reports that PUF60 promotes tumor growth, its precise mechanism in tumors is remains unknown." (PMID 37632669, 2024). "Altogether, these results indicated that the expression of PUF60 and TERT showed a positive correlation in both RCC cell lines and tumor tissues." (PMID 33061812, 2020). "To further explore the association of the protein expression of PUF60 and TERT, we conducted the Pearson correlation analysis of PUF60 and TERT expression in RCC tumor tissues, and a significant correlation was observed (r=0.5182, P<0.0001)." (PMID 33061812, 2020). "PUF60 and MAZ together play a critical role in the regulation of tumor progression." (PMID 40411278, 2025). "PUF60 contributes to apoptosis and transcriptional regulation, SFXN3 is a mitochondrial serine transporter, SERPINB1 regulates the innate immune response, SERPINB5 is a tumor suppressor, and STXBP2 regulates exocytosis." (PMID 36400567, 2023). "In Basal-like BRCA, PUF60 was upregulated and PNN was downregulated in tumor samples." (PMID 34630526, 2021). "Our previous results showed that PUF60 could regulate the expression of TERT and the mRNA expression of PUF60 and TERT showed a positive correlation, while their protein expression correlation in RCC cell lines and tumor tissues remained to be elucidated." (PMID 33061812, 2020). "Although PUF60 expression didn't show significant higher expression compared to normal tissues in KIRP, PUF60 did show significant higher expression in the paired KIRC tumor tissues compared to corresponding normal tissues." (PMID 33061812, 2020). "Knockdown of PUF60 decreased the tumor volume and weight significantly, while overexpression of PUF60 increased the tumor volume and weight, though the mouse body weight showed no obvious difference between different groups." (PMID 33061812, 2020). "Furthermore, we showed that there was a strong correlation of the expression of PUF60 and TERT in RCC tumor tissues and RCC cell lines, and the patients with high expression of PUF60 and TERT had significantly shorter survival." (PMID 33061812, 2020).
tumor (continued). "However, the PUF60, BOP1, and E2F1 genes were found to be significantly over-expressed in tumor tissues with copy number gains." (PMID 26360582, 2015). "In contrast to PUF60, the BOP1 and E2F1 were found to be over-expressed in tumor tissues with copy number gains as well as in those without." (PMID 26360582, 2015). "The results showed that, regardless of the chip or protein levels, VPS28, HSF1, and PUF60 showed higher expression in tumour tissues than in normal tissues, while COL17A1 and SMOC1 showed significantly higher expression in the adjacent tissues compared with the tumour tissues." (PMID 32964046, 2020).
infection (3 papers, 2017 to 2024). The state of being infected such as from the introduction of a foreign agent such as serum, vaccine, antigenic substance or organism. "Overexpression of either wildtype or the mutated PUF60 (G300D) improves cell survival at 24 hr post-infection." (PMID 32538777, 2020). "The induction of IL-8, IL-6, CXCL2 and IL-1α upon infection was significantly suppressed by overexpressing the mutated PUF60." (PMID 32538777, 2020). "Although rnp-6 levels remain stable after infection in C. elegans, infection reduces the abundance of PUF60 in various mammalian cells." (PMID 32538777, 2020). "At earlier time points, such as day 2 post-infection, it was difficult to assess the influence of PUF60 expression since basal levels of HBV RNAs were quite low in this setting." (PMID 28993636, 2017). "We hypothesize that infection induced down-regulation of PUF60 might be a recent evolutionary adaptation of the immune system." (PMID 32538777, 2020). "We first asked if PUF60, the mammalian homolog of rnp-6, is regulated during infection." (PMID 32538777, 2020). "Therefore, mammalian PUF60 responds to infection by reducing its expression, while C. elegans rnp-6 levels remain stable after infection." (PMID 32538777, 2020). "Also, overexpression of wildtype or the mutated form of PUF60 improved HeLa cell survival upon S. aureus infection at a later time point (post-infection 24 hr) without affecting bacterial internalization." (PMID 32538777, 2020). "Similar results were observed in C. elegans, where RNAi against rnp-6 also induced infection responsive genes, indicating an evolutionarily conserved role of RNP-6/PUF60 of suppressing basal immune-gene expression." (PMID 32538777, 2020). "PUF60 knockdown in HeLa cells without infections induced the pro-inflammatory cytokines IL-8, IL-6, CXCL2, and IL-1α." (PMID 38396730, 2024). "We discuss the role of PUF60 in immunity with and without infection based on recent organismic and cellular studies." (PMID 38396730, 2024).
bacterial infection (2 papers, 2020 to 2024). "This may suggest that patients with PUF60 deficiency have a dysregulated immunological response during bacterial infections of the respiratory tract, ears, or urinary tract, as observed in our cohort." (PMID 38396730, 2024). "The mammalian homolog, PUF60, also displays anti-inflammatory properties, and its levels swiftly decrease after bacterial infection in mammalian cells, implying a role in the host response." (PMID 32538777, 2020). "Reduction of PUF60 by RNAi is sufficient to induce pro-inflammatory cytokine expression, suggesting that PUF60 reduction induced by bacterial infection is a trigger of inflammation." (PMID 32538777, 2020).
heart disease (1 paper, 2021). "Further potentially disease-relevant protein candidates without a known functional relation to hypertrophy, fibrosis or decompensated heart disease were SLTM, HNRNPLL, FIP1L1, RNMT, KRT18 and PUF60 and the downregulated NUDT4, GCAT, KIDINS220 and ARVCF." (PMID 34937869, 2021).
metabolic disease (1 paper, 2026). A congenital disorder (due to inherited enzyme abnormality) or acquired (due to failure of a metabolically important organ) disorder resulting from an abnormal metabolic process. "The hypothesis that FIR/PUF60 regulates translation efficiency through splicing control is an intriguing topic for elucidating the molecular mechanisms of cancer and metabolic diseases." (PMID 41596295, 2026).
neurodevelopmental disorder (1 paper, 2024). A behavioral and cognitive disorder with onset during the developmental period that involves impaired or aberrant development of intellectual, motor, or social functions. "We propose to re-classify the disease entity as PUF60-related neurodevelopmental disorders with additional multi-system involvement." (PMID 38396730, 2024). "We propose that, if considering all domains of neurodevelopmental disorders, this phenotype is a key feature in diagnosing even milder PUF60-related disorders, and we consider it the singular core feature in the re-classification of the spectrum of PUF60-related disorders." (PMID 38396730, 2024).
PUF60 also shares sentences with these, for which no sentence is quoted: coloboma (3 papers); amyotrophic lateral sclerosis (2); colon cancer (2); lymph node metastasis (2); mandibulofacial dysostosis (2); microcephaly (2); atrioventricular septal defect (1); Cerebro-costo-mandibular syndrome (1); colorectal cancer (1); Creutzfeldt-Jakob disease (1); diffuse large B-cell lymphoma (1); eczema (1); eosinophilia (1); esophageal cancer (1); hepatocellular carcinoma (1); Hirsutism (1); lymphoid neoplasm (1); microdeletion syndrome (1); myotonic dystrophy (1); Nager syndrome (1); optic nerve hypoplasia (1); Ovarian cyst (1); ovarian tumors (1); pancreatic adenocarcinoma (1); Parkinson disease (1); proteinopathies (1); thymoma (1); upper respiratory tract infections (1); urothelial carcinoma (1); uterine carcinosarcoma (1).
A further 1 disease shares a sentence with PUF60 in 1 paper.